EPCAM (epithelial cell adhesion molecule)
Diseases named in the same sentence as EPCAM in open-access papers (continued):
Sharing a sentence is not in itself a finding about the gene and the disease.
tumor (continued). "The subdivision of all EpCAM+ cells into 20 subgroups suggests high epigenetic heterogeneity within the tumor cells." (PMID 30389926, 2018). "We stained a single-cell suspension of the dissected tumor with anti-EpCAM and anti-CD45 as above and performed Pi-ATAC on 384 cells." (PMID 30389926, 2018). "Specific molecules including CD34, CD44, CD166, ALDH1, and EpCAM that are expressed in a variety of tumor cells are considered as the primary biomarkers for the identification of CSCs." (PMID 30515411, 2018). "Conventional circulating tumor cell (CTC) detection strategies rely on cell surface marker EpCAM and intracellular cytokeratins (CKs) for isolation and identification, respectively." (PMID 28852197, 2017). "Upregulation of TET2 in the KDM2A-depleted cells induces the re-activation of two TET downstream tumor suppressor genes, epithelial cell adhesion molecule (EpCAM) and E-cadherin, and inhibits migration and invasion." (PMID 28785073, 2017). "This demonstrates that the EpCAM BiTE (either free or encoded within an oncolytic virus) can mediate activation of PBMC‐derived T cells and selective cytotoxicity to human tumour cells in malignant peritoneal ascites." (PMID 28634161, 2017). "Catumaxomab, which isspecific for the EpCAM target antigen, was approved for thetreatment of malignant ascites in cancer patients with EpCAM-positive tumours in the European Union in 2009." (PMID 28403178, 2017). "Multiple different cell types residing within the lung TME express PDL1, including macrophages, monocytes, neutrophils and epithelial cell adhesion molecule (EpCAM)+ tumour cells." (PMID 28146145, 2017). "Then EpCAM+ tumor cells were sorted via fluorescence activated cell sorting and inoculated into Nude mice." (PMID 29108242, 2017). "The apoptotic effect of soluble TRAIL on tumour cells was significantly increased in vivo after pretreatment with EpCAM-targeted particles, as BLI signals were significantly reduced 7 days post injection." (PMID 28317839, 2017). "Enriched EpCAM+ Dt81Hepa1-6 cells led to higher tumor load than EpCAM- Dt81Hepa1-6 cells (1093±74 vs 473±100 tumors; P<0.01)." (PMID 28152020, 2017). "To explore these populations in the transplanted tumours, we collected tumours from each mouse, dissociated and analysed EpCAM+/CD31−/CD45− cells for expression of NGFR and Sca1." (PMID 28387316, 2017). "Given that EpCAM is expressed on tumour cells of epithelial origin with negligible expression on blood cells in the vascular microenvironment, this particle platform enables targeting of EpCAM+ tumour cells in the vasculature." (PMID 28317839, 2017). "The scanned ELISPOT plates of EpCAM-positive tumor cell lines showed that there was stronger development of spots with EpCAM-specific CAR-equipped T cells than with the control T cells transfected with mGFP RNA CAR." (PMID 28088790, 2017). "Epithelial cell adhesion molecule (EpCAM) overexpression correlated with an escalation in epithelial cell proliferation during tumor development." (PMID 28506269, 2017). "This parameter has been calculated as CD16 expressing TAM cells versus EpCAM+ tumor cells measured by flow cytometry in 8 OC patients." (PMID 29245952, 2017). "Unsorted Dt81Hepa1-6 cells resulted in tumor loads that were proportional to the levels of EpCAM positive cells within the unsorted population." (PMID 28152020, 2017). "Recovery rate comparison of ccRCC tumor cell lines revealed the lowest median recovery using the EpCAM based enrichment approach in three out of four ccRCC cell lines." (PMID 29152114, 2017). "In line with the tumor incidence between these two subpopulations, mice injected with EpCAM+/shZFX cells displayed progressive lower tumor burden than the mice transplanted with control cells." (PMID 28156061, 2017). "EpCAM mRNA expression, a known marker of enhanced tumorigenicity and tumor initiating cells, was first evaluated." (PMID 28152020, 2017).
tumor (continued). "As sorafenib enriched the population of EpCAM+ CSCs, it is possible that CSCs play a central role in the secretion of EVs and affect tumor growth and metastasis in HCC." (PMID 28900199, 2017). "Multiple novel tumor-specific proteins are proposed and EPCAM was demonstrated to be specifically overexpressed in primary tumors and lymph node metastases." (PMID 28336725, 2017). "Differential gene expression analysis generated 128 genes that segregated bulk tumor regions from EPCAM+CD44+CD49f+ cells." (PMID 28487492, 2017). "Somatic variants present in both the bulk tumor and tumor EPCAM+CD44+CD49f+ subpopulations were categorized as shared (37/51, 72.5%), enriched in the bulk tumor (5/51, 9.8%), or enriched in the tumor EPCAM+CD44+CD49f+ cells (9/51, 17.6%)." (PMID 28487492, 2017). "The I2 estimate revealed no heterogeneity (I2 = 0%) among the studies, and the fixed effect model used in the meta-analysis indicated that expression of EpCAM in the tumour size >5 cm group was greater than that in the tumour size ≤ 5 cm group." (PMID 28403178, 2017). "With respect to the lobular subtype, EMA, Her2/neu or EpCAM was present in 100% of tumor cells in 4 out of 10 ovarian metastases." (PMID 28327103, 2017). "In contrast, EPCAM was very highly expressed in tumor cells with only moderate staining in basal epithelial squamous cells and gastric epithelial cells." (PMID 28336725, 2017). "By performing immunohistochemistry analysis of primary RCC tissue, EpCAM expression was detected in only 29% of the tumor samples, which is in line with previous reports showing low expression of EpCAM in ccRCC tissues." (PMID 29152114, 2017). "Circulating tumor cells (CTCs), potential precursors of most epithelial solid tumors, are mainly enriched by epithelial cell adhesion molecule (EpCAM)-dependent technologies." (PMID 28858218, 2017). "Lung-derived gMDSCs also enhanced the expression of EpCAM in tumour cells in co-culture experiments." (PMID 28382931, 2017). "Attributed to the robust inhibitory effect of T cells stably expressing anti-EpCAM CAR on tumor growth, the survival of tumor-bearing mice in the anti-EpCAM CAR group was significantly improved." (PMID 28088790, 2017). "While sorted cell populations ranged from 0.04% to 0.27% as expected in the four primary tumor regions, we detected a smaller proportion of EPCAM+CD44+CD49f+ cells in the lymph nodes ranging from 0.002% to 0.004%." (PMID 28487492, 2017). "Despite genomic similarity between the bulk tumor and the EPCAM+CD44+CD49f+ cells, principal component analysis demonstrated heterogeneity among bulk tumor regions, lymph nodes, as well as the derived EPCAM+CD44+CD49f+ subpopulations." (PMID 28487492, 2017). "In this context, aptamer targeting EpCAM was shown to inhibit CSCs when linked to siRNAs against PLK1, a kinase required for mitosis, and cause tumor regression when injected in the TNBC xenograft model." (PMID 28974015, 2017). "Using this method, molecular tumor cell markers, such as epithelial cell adhesion molecule (EPCAM), can be used to identify metastatic cells in the CSF for diagnosis." (PMID 29069871, 2017). "In an attempt to study the possible relationship between EpCAM and MSC recruitment to HCC, surface expression of EpCAM on MSC and tumor cells were first examined by FACS analysis using FITC-conjugated EpCAM antibodies." (PMID 28903370, 2017). "On the contrary, we found a tendency towards a higher grafting capability for tumours according to the presence of CD133+/CXCR4+/EpCAM− cells." (PMID 28751748, 2017). "By targeting EpCAM with the aptamer as well as with a siRNA of EpCAM, the systemically delivered chimera resulted in the regression of tumor xenografts derived from MCF-7." (PMID 29218233, 2017).
tumor (continued). "Although EpCAM is attractive for targeted cancer therapy, the fact that EpCAM is expressed also on normal epithelium, though to a much lower level, is a concern for potential on-target/off-tumor toxicity of targeted therapy against EpCAM-positive tumors." (PMID 28088790, 2017). "CD68 (+) or CD163 (+) tumor stromal TAMs were all enriched together with EpCAM, K19 and CD133 expression (P <0.05 for all)." (PMID 28114366, 2017). "Subsequently, multi-marker RT-PCR analysis was used to detect tumor-associated transcripts, including KRT19, MUC1, EpCAM, CEACAM5, and BIRC5." (PMID 28626429, 2017). "CTCs that fail to be captured by EpCAM‐dependent methods are detectable with antibodies directed against mesenchymal as well as other tumor markers, suggesting that CTCs are indeed heterogeneous for epithelial and mesenchymal markers." (PMID 28544498, 2017). "On the contrary, in 4/5 TNBC PDXs that we tested, CD49f+/EpCAM+/E-cadherinhigh cells have the highest tumor initiating capacity." (PMID 29162812, 2017). "The EpCAM system harvest contained very high numbers of magnetic beads bound to the tumor cells, making an estimation of contaminating leukocytes impossible." (PMID 29152114, 2017). "Co-culture of the RNA CAR-modified T cells with EpCAM-positive tumor cell lines HRT-18G and SKOV3-Luc stimulated much higher levels of granzyme B release when compared with co-cultures of mock transfected T cells and T cells transfected with mGFP RNA CAR." (PMID 28088790, 2017). "Immunofluorescence staining in archival NPC specimens revealed that subsets of tumour cells co-expressing high EpCAM and low KLF4 protein levels were also present in NPC patients." (PMID 28959019, 2017). "These properties are associated with increased expression of EpCAM and β-catenin confirming that EpCAM+ HCC cells comprise a subset with characteristics of tumor-initiating cells with stem/progenitor cell features." (PMID 28152020, 2017). "Novel tumor-specific proteins are proposed and EPCAM was demonstrated to be specifically overexpressed in primary tumors and lymph node metastases compared with surrounding normal tissues." (PMID 28336725, 2017). "In this platform, tumor cells are first immunomagnetically enriched by EpCAM antibody-coupled magnetic beads." (PMID 27738343, 2017). "We found that most of the primary tumor cells expressed EpCAM, whereas approximately 10% of cells expressed CD90 in control mice." (PMID 28900199, 2017). "Clearly, it is expected that only patients with high-level EpCAM expression on tumor cells would benefit from antibody treatment and therefore randomization appears mandatory." (PMID 28531111, 2017). "The low frequency of tumor formation with cirrhotic EpCAM+ cells cannot be fully explained by number of injected cells alone." (PMID 28176469, 2017). "Because of the wide variance of EpCAM expression in the primary tumor, the expression of EpCAM in lymph node metastases of urothelial cell bladder cancer has not been determined yet, as far as we know." (PMID 28820475, 2017). "The purpose of the present study was to compare genomic alterations in two cell fractions enriched of CD133+ and CD133−/EpCAM+ cells, respectively, obtained from fresh intraoperative human tumour biopsies." (PMID 28347289, 2017). "MHC class I expression in EpCam+ tumour tissues was lower than that in EpCam+ normal tissues, suggesting that Tim-3 and PD-1 expression on intratumoural NK cells was presumably induced by MHC class I downregulation in the tumour tissues of cancer patients." (PMID 28585539, 2017). "Transduction with BV-EpCAM resulted in much higher mean fluorescence intensities of EpCAM expression on the tumor cells." (PMID 28088790, 2017). "Tumour-selective pro-apoptotic activity of scFvFITC:sFasL was confirmed in a panel of 4 carcinoma cell lines pretargeted with either anti-EpCAM-FITC or anti-CD44-FITC." (PMID 29038485, 2017).
tumor (continued). "Together, these results indicate that tumor tropism of MSC is influenced by the activation of EpCAM signaling pathway through the enzymatic activities." (PMID 28903370, 2017). "IL-6 (+) tumor stromal cells were enriched together with EpCAM, K19 and CD133 expression (P <0.05 for all)." (PMID 28114366, 2017). "Further experiments are needed to reveal the related mechanisms with respect to how the abundant peritumoral EpCAM or CD13 provide fertile soil for tumor cells." (PMID 28572700, 2017). "Tumor cells were enriched by EpCAM+ (epithelial cell adhesion molecule) FACS sorting from single cell suspensions and then inoculated to Nude mice in a gradient dose." (PMID 29108242, 2017). "EpCAM and CD13 are some stemness-related markers in HCC, and several studies have demonstrated that EpCAM or CD13 expression in HCC tumor tissue is associated with a poor prognosis." (PMID 28572700, 2017). "A study demonstrated that lymphocytes overexpressing TRAIL in combination with EpCAM × CD3 bispecific antibody prolonged the exposure time of TRAIL with its receptors on tumor cells and enhanced the antitumor response." (PMID 28931402, 2017). "An in vivo serial transplantation assay was performed using CD24, CD44 and EpCAM-selected cells from xeno-B110 to determine if they were able to self-renew by initiating new tumours up to the fourth generation." (PMID 28959019, 2017). "Immune cells (CD45+) were the predominant cells versus tumor cells (EpCAM+) both in solid tumors and ascites but with large variability between patients." (PMID 29245952, 2017). "Previously, it has been shown that elevation of EpCAM expression enhances tumor sphere formation and tumor initiation." (PMID 28157205, 2017). "The MOC31PE immunotoxin targets and kills tumor cells expressing the epithelial cell adhesion molecule (EpCAM), which is highly expressed in EOC, and MOC31PE is being investigated for use in treatment of PM-EOC." (PMID 28977905, 2017). "The principal of this system is based on the epithelial cell adhesion molecule (EpCAM) on the tumor cell surface and cytokeratins (CKs) expressed in the same tumor cell." (PMID 28187533, 2017). "Currently, several trials have been conducted to target EpCAM-expressing tumor cells using specific antibodies." (PMID 29245156, 2017). "GFP- and luciferase-expressing COLO 205 tumour cells were injected systemically into the tail vein of nu/nu mice, followed 15 min later by an injection of EpCAM-targeted, PEG-functionalized PLGA particles." (PMID 28317839, 2017). "Histologically, the original HCC sample showed EpCAM expression in tumor epithelial cells and CD90 expression in mesenchymal cells." (PMID 28900199, 2017). "The epithelial cell adhesion molecule (EpCAM) is overexpressed in a wide variety of tumor types, including peritoneal carcinomatosis (PC) from gastrointestinal and gynecological malignancies." (PMID 28088790, 2017). "In this regard, Solitomab (MT110, AMG 110), an EpCAM/CD3-bispecific single-chain antibody, is able to bind polyclonal CD8+ and CD4+ T cells and activate them, addressing against EpCAM-expressing tumor cells." (PMID 28531111, 2017). "They reported sporadic reactivity for AR, cytokeratin and EpCAM and suggested rare, undifferentiated clones from the donor tumour had established the xenograft." (PMID 29145505, 2017). "After binding to the surface of EpCAM-expressing tumor cells, MOC31PE is internalized and rapidly triggers cell death even in chemotherapy resistant cancer cells, broadening the potential utility of the drug." (PMID 28977905, 2017). "The basal levels of EpCAM mRNA expressions in representative animals were confirmed by real-time PCR analysis at the beginning of the tumor development (Figure 3Aii)." (PMID 28903370, 2017). "Human tumor expression of AMHRII was confirmed by colocalization of EpCAM and AMHRII positive cells (except for PDX OV54 which lacks EpCAM expression)." (PMID 29245952, 2017).
tumor (continued). "In one study, using EpCAM as a chimeric antigen receptor to induce T cell targeting of EpCAM+ tumor cells resulted in inhibition of PC3M tumor growth leading to increased murine survival." (PMID 28690641, 2017). "Principle of the CellSearch system is based on specific combination of antibody to epithelial cell adhesion molecule (EpCAM) on the tumor cell surface, and identification of cytokeratin (CK) in the tumor cell membrane and cytoplasma." (PMID 28423493, 2017). "EpCAM expression is, at least in part, responsible for the observed heterogeneity of tumor cell metabolism." (PMID 28279189, 2017). "Through this test, tumor cells are isolated by immunomagnetic enrichment from body fluids using ferrofluid nanoparticles coated with epithelial cell adhesion molecule (EpCAM)-specific antibodies." (PMID 28577209, 2017). "One of the important findings from this study is delayed disease progression in tumor-bearing mice by repeated injections of T cells with transient expression of anti-EpCAM CAR by mRNA electroporation." (PMID 28088790, 2017). "All five of the proteins predicted to be upregulated in EAC compared with normal esophagus (SAMHD1, ARHGDIB, AGR2, HSPA5, EPCAM) showed higher expression in the tumor sections compared with squamous epithelium." (PMID 28336725, 2017). "Several studies pointed that EpCAM was identified as a one of tumour stem cell markers and an potential target for cancer therapy." (PMID 28403178, 2017). "OCT4 gene expression was below detection limit in all cell samples, except 5 samples (2 CD133+, 3 CD133−/EpCAM+; all from different patient tumour biopsies)." (PMID 28347289, 2017). "Mean latency, growth curve and adjusted MAI’s differences were less discerning between EpCAM/CD44dbr and EpCAM/CD44ddim tumours from C666-1." (PMID 28959019, 2017). "Quantitative analysis showed a >90% reduction in BLI signal for tumour cells treated with EpCAM-targeted particles followed by soluble TRAIL administration in vivo as compared with controls." (PMID 28317839, 2017). "Recent research has demonstrated that the downregulation of EpCAM significantly suppresses adhesive, invasive and migratory abilities of cell lines and tumour formation and metastatic abilities in nude mice." (PMID 28403178, 2017). "The objective of this study was to investigate EpCAM-positive circulating tumor cells (CTC) as liquid biomarker to identify patients with high risk of recurrence after liver resection." (PMID 29163804, 2017). "This is the first study where so many samples are analyzed in the primary tumour setting in EpCAM-positive CTCs and in corresponding plasma using the same blood draw, identical methodologies and three genes." (PMID 29069768, 2017). "In conclusion, the findings of the present study have shown that the selected aptamer (Ep1) binds specifically to EpCAM-expressing tumor cells." (PMID 29245156, 2017). "Allele frequencies of somatic single nucleotide variants were analyzed in order to further determine if EPCAM+CD44+CD49f+ cells isolated from the lymph nodes were analogous to EPCAM+CD44+CD49f+ cells isolated from the primary tumor." (PMID 28487492, 2017). "Two Chinese studies have investigated the predictive power of EpCAM-positive CTC for tumor recurrence after liver resection, and revealed a significant association with early tumor recurrence after liver resection." (PMID 29163804, 2017). "We observed that sorafenib subtly affected the suppression of primary tumor growth maintained by EpCAM+ CSCs, but completely inhibited the lung metastasis mediated by CD90+ CSCs." (PMID 28900199, 2017).